SCAI (suppressor of cancer cell invasion)
Description:
Tumor suppressor which functions to suppress MRTFA-induced SRF transcriptional activity. May function in the RHOA-DIAPH1 signal transduction pathway and regulate cell migration through transcriptional regulation of ITGB1.
Synonyms: C9orf126; FLJ36664; NET40
Tractability: Antibody: UniProt predicts a signal peptide or a membrane-spanning region. PROTAC: ubiquitination databases record sites on it; its protein half-life has been measured.
Gene: Protein-coding gene on chromosome 9 (124,942,608 to 125,143,528, reverse strand). Ensembl gene ENSG00000173611.
Subcellular location: Membrane; Nucleus; Cytoplasm
Subcellular location (Human Protein Atlas): Nuclear membrane; Nucleoplasm
Pathways (Reactome):
Signal Transduction: RHO GTPases Activate Formins
Gene Ontology:
Molecular function: protein binding; transcription corepressor activity
Biological process: negative regulation of cell migration; negative regulation of Rho protein signal transduction; DNA-templated transcription; negative regulation of DNA-templated transcription
Cellular component: cytoplasm; nucleoplasm; nucleus; membrane
Genetic constraint (gnomAD): Loss-of-function variants: 8 observed, 20.71 expected, observed/expected ratio (o/e) 0.39, 90% interval 0.23 to 0.7. The upper end of that interval is the gene's LOEUF score, 0.7, which puts it in group 2 of 6, group 1 being the genes least tolerant of losing a copy. Missense variants: 170 observed, 260.59 expected, observed/expected ratio (o/e) 0.65, 90% interval 0.57 to 0.74. Synonymous variants: 94 observed, 95.96 expected, observed/expected ratio (o/e) 0.98, 90% interval 0.83 to 1.16.
Homologues: Orthologues: macaque SCAI (99% identical), chimpanzee SCAI (99% identical), pig SCAI (99% identical), rabbit SCAI (99% identical), mouse Scai (98% identical), guinea pig SCAI (95% identical), rat Scai (94% identical), dog SCAI (93% identical), tropical clawed frog scai (85% identical), zebrafish scai (76% identical), Drosophila melanogaster CG13293 (50% identical).
Diseases named in the same sentence as SCAI in open-access papers:
SCAI is named in the same sentence as 29 diseases in open-access papers, as found by Europe PMC text mining. Sharing a sentence is not in itself a finding about the gene and the disease. The quoted sentences say what the papers report.
ovarian carcinoma (7 papers, 2020 to 2025). A malignant neoplasm originating from the surface ovarian epithelium. "siRNA-mediated SCAI depletion also caused a similar phenotype in TOV-21G ovarian cancer cells." (PMID 36215310, 2022). "Mechanism studies confirmed that CDR1as can regulate the sensitivity of ovarian cancer to cisplatin through the miR-1270/SCAI signaling pathway and promote ovarian cancer development." (PMID 32670861, 2020). "circCdr1as is involved in the formation of DDP resistance in ovarian cancer; functioning as a miRNA sponge to downregulate miRNA-1270 and upregulate suppressor of cancer cell invasion (SCAI), the target gene of miRNA-1270, it can enhance the sensitivity of ovarian cancer cells to DDP." (PMID 35382838, 2022). "We found that both siRNA-mediated depletion and CRISPR-Cas9 KD of SCAI significantly compromised RF progression post-UV in U-2 OS cells as well as in 2 additional cancer cell lines: TOV-21G (ovarian cancer) and WM3248 (melanoma)." (PMID 36215310, 2022).
breast carcinoma (5 papers, 2013 to 2025). "We show here that SCAI is expressed in a wide range of normal human tissues and its expression is diminished in a large array of primary human breast cancer samples indicating that SCAI expression might be linked to the etiology of human cancer." (PMID 23936361, 2013). "SCAI expression was diminished in human breast cancer cells, and it was shown to regulate cancer cell invasion through an interaction with the SWI/SNF complex." (PMID 28423650, 2017). "By targeting the SCAI protein, miR-1228 facilitates the advancement of breast cancer." (PMID 39866239, 2025).
hepatocellular carcinoma (4 papers, 2017 to 2025). A malignant tumor that arises from hepatocytes. "It has been reported that miR-425 promoted invasion and metastasis in hepatocellular carcinoma via modulation of SCAI, while it inhibited melanoma metastasis by negatively regulating IGF-1 through repression of PI3K-Akt pathway 25,26." (PMID 32284738, 2020). "miR425 through down-regulation of SCAI or forkhead box D3 (FOXD3) promoted proliferation, migration, and hepatocellular carcinoma cell metastasis." (PMID 37582765, 2023).
osteosarcoma (4 papers, 2020 to 2025). A usually aggressive malignant bone-forming mesenchymal neoplasm, predominantly affecting adolescents and young adults. "Recent studies show that SCAI, as the target gene of miR-1228, is down-regulated by miR-1228 and promoted the invasion and migration of osteosarcoma cells." (PMID 33274736, 2021). "miR-1228 expression was significantly increased in CAFs, their secreted exosomes, and recipient osteosarcoma cells; leading to a down-regulation of SCAI mRNA and protein expression in osteosarcoma cells, promoting cell migration and invasion." (PMID 32957712, 2020). "Moreover, the direct targeting of SCAI by exosome miR-1228 prompts the migration and invasion of osteosarcoma." (PMID 39866239, 2025).
melanoma (3 papers, 2020 to 2025). A malignant, usually aggressive tumor composed of atypical, neoplastic melanocytes. "We found that ADAM10 and SCAI expression was increased in the primary melanomas from patients with OS > 5 years compared to tumors from patients with OS < 5 years (Mann-Whitney U test p-value < 0.05)." (PMID 40075679, 2025). "Of the nine putative proteomic biomarkers studied in an independent cohort using IHC, CDK4, ADAM10, SCAI, and DDX11 seem promising starting points for further investigation of their role in melanoma routine diagnostics." (PMID 40075679, 2025).
essential hypertension (2 papers, 2022). Hypertension that presents without an identifiable cause. "SCAI is a transcriptional modulator regulating myocardin, implicated in cardiac hypertrophy and hypertension." (PMID 35000590, 2022). "However, Zorc-Plesković and colleagues found a trend (p=0.07) towards an association between the A1A1 genotype of the ScaI gene polymorphism and childhood essential hypertension but statistical significance was not reached." (PMID 35181806, 2022).
glioma (2 papers, 2015 to 2021). A benign or malignant brain and spinal cord tumor that arises from glial cells (astrocytes, oligodendrocytes, ependymal cells). "SCAI, a possible tumor suppressor in regulating tumor cell invasion, was reported to make a difference in glioma cells by activating Wnt/β-catenin signaling." (PMID 33274736, 2021).
oral squamous cell carcinoma (2 papers, 2020 to 2023). "Next, miR5100 stimulated the proliferation and migration of oral squamous cell carcinoma cells by down-regulation of the suppressor of cancer cell invasion (SCAI) mRNA." (PMID 37582765, 2023). "In oral squamous cell carcinoma cells, SCAI is targeted by miRNA-25-3p and induces cell migration by activating the E-cadherin pathway." (PMID 33103723, 2020).
atherosclerosis (1 paper, 2025). A disease characterized by the build-up of fatty material and calcium deposition in the arterial wall resulting in partial or complete occlusion of the arterial lumen. "Of the 25 shared novel atherosclerosis loci with evidence of colocalization, 7 analyses strongly colocalized with PRPA ≥0.80 (nearest gene: BNC2, SCAI, TSC22D2, SRRM1, ABCB11, PRRX2)." (PMID 40313769, 2025).
cervical (1 paper, 2016). "In our study, we discovered several integration sites located inside the introns of tumor suppressor genes (including the famous SCAI gene), implying a link between HPV integration and cervical oncogenesis, probably through manipulating the expression of cancer related genes." (PMID 27884161, 2016).
cervical cancer (1 paper, 2023). A primary or metastatic malignant neoplasm involving the cervix. "- Inhibition of miR-766-5p lead to induction of apoptosis and suppression of proliferation, invasion and migration of cervical cancer cells by downregulation SCAI level." (PMID 37205191, 2023).
lung carcinoma (1 paper, 2025). "SCAI protein has a debated role in cancer prognostics, correlating with a better outcome in breast and lung cancers." (PMID 40075679, 2025).
oral cancer (1 paper, 2023). "In oral cancer, miR-5100 has been reported to directly target the suppressor of cancer cell invasion (SCAI), which regulates cell migration and proliferative capacity and promote OSCC cell growth and invasion by suppressing SCAI." (PMID 37568586, 2023).
papillary thyroid carcinoma (1 paper, 2020). "In papillary thyroid carcinoma cells, SCAI mediated cell proliferation and migration by binding to miR-574-5p via Wnt/β signaling pathway." (PMID 33103723, 2020).
renal fibrosis (1 paper, 2017). A final common manifestation of a wide variety of chronic kidney diseases characterized by glomerulosclerosis and tubulointerstitial fibrosis. "As a negative regulator of MRTF, SCAI can regulate EMT and renal fibrosis." (PMID 28423650, 2017).
cancer (30 papers, 2013 to 2025). A tumor composed of atypical neoplastic, often pleomorphic cells that invade other tissues. "By using qRT-PCR, we discovered that the expression of SCAI was down-regulated in NSCLC cancer cells, and negatively associated with the expression of miR-371b-5p." (PMID 33103723, 2020). "Exosomes released by cancer-associated fibroblasts transfer miR-1228 to OS cells, leading to the promotion of OS migration and invasion through the inhibition of endogenous suppressor of cancer cell invasion (SCAI) expression." (PMID 38203737, 2024). "SCAI encodes a protein that suppresses cancer cell invasion." (PMID 36358356, 2022). "A brand-new protein that is highly conserved, called SCAI (suppressor of cancer cell invasion) mediates metastasis by acting as a 3-dimensional matrix." (PMID 37205191, 2023). "It has been suggested that the suppressor of cancer cell invasion (SCAI) has a tumor-suppressive function in TC because it inhibits the myocardin-related transcription factor (MRTF), which regulates cancer cell invasion." (PMID 37644548, 2023). "SCAI, a suppressor of cancer cell invasion, inhibits tumor cell invasion, and its expression is decreased in many types of tumors." (PMID 37047677, 2023). "Besides, the integration of the SMAD4-PΨg in the SCAI gene has been corroborated in hereditary cancer-predisposition cases, and while SCAI is characterized to have suppressive effect on tumor cell invasiveness, it has not been determined whether SCAI expression is hindered by the SMAD4-PΨg." (PMID 35114952, 2022). "Following this axis, another study further confirmed that PTCSC/miR-574-5p mediated the PTC-1 cell cycle through targeting suppressor of cancer cell invasion (SCAI), thus promoting the proliferation and migration of PTC via Wnt/β-catenin pathway." (PMID 36671425, 2022). "miR5100 mediates proliferation and migration of oral squamous carcinoma cells via downregulation of SCAI (suppressor of cancer cell invasion)." (PMID 35190967, 2022). "Suppressor of cancer cell invasion (SCAI) is a binding partner and inhibitor of MRTF, which reduces cancer cell migration primarily by suppressing the MRTF-induced β1 integrin production in cancer cells." (PMID 34204945, 2021). "It has been reported that the suppressor of cancer cell invasion (SCAI) protein can form a complex with MRTF and SRF to inhibit the invasion of human BC cells." (PMID 34475953, 2021). "We then detected the expression level of SCAI mRNA in the NSCLC tissues and H466 and H1299 cell lines, and found that SCAI was decreased in cancer cells than in the normal cells." (PMID 33103723, 2020). "An interesting gene (HORVU5Hr1G062040) that was up-regulated in CamB roots shows similarity to human SCAI, the suppressor of cancer cell invasion gene that inhibits the invasive migration of tumor cells." (PMID 31817496, 2019). "SCAI was previously shown to suppress cancer cell invasion through transcriptional regulation of integrin β1 (ITGB1)." (PMID 28423650, 2017). "SCAI is a newly identified tumor suppressor that plays an important role in regulating cancer cell invasion." (PMID 28423650, 2017). "Emerging evidence has indicated that SCAI inhibited migration and invasion in human cancers, and SCAI is downregulated in a variety of human tumors." (PMID 26314959, 2015). "SCAI (suppressor of cancer cell invasion) has been recently characterized as a protein that inhibits the invasive migration of human tumor cells through the control of MAL/SRF signaling." (PMID 23936361, 2013). "We have recently characterized SCAI (Suppressor of Cancer Cell Invasion), a transcriptional modulator regulating cancer cell motility through suppression of MAL/SRF dependent gene transcription." (PMID 23936361, 2013).
cancer (continued). "On the other hand, the increased candidates included proteins involved in the blockade of cancer cell migration and invasion (SCAI, CARMIL2), autophagy activation (HSBP1, RILP) as well as proteins that can be considered as anti-tumorigenic (SCG2, DIP2A, HSBP1)." (PMID 39833546, 2025). "In many different types of cancer, SCAI is down-regulated and functions as an anti-tumor gene." (PMID 37205191, 2023). "The SCAI gene, might therefore lead to an upregulation of downstream genes involved in cancer development." (PMID 35114952, 2022). "In OC, unlike the negative effect of circ-CDR1as on BC chemotherapy, overexpression of circ-CDR1as can enhance DDP-induced cell apoptosis via modulating suppressor of cancer cell invasion (SCAI) and miR-1270, and this Cdr1as/miR-1270/SCAI axis is responsible for sensitizing OC to DDP." (PMID 32122355, 2020). "SCAI is located at the 9q33.3 position and can act as a suppressor during cancer cell metastasis." (PMID 33103723, 2020). "We further explored whether miR-625-3p exerts its oncogenic function via inhibiting its target SCAI (suppressor of cancer cell invasion)." (PMID 26314959, 2015). "In cancer cells, MKL1 signaling has been shown to be inhibited by nuclear complex formation with SCAI, and in the original study a qPCR based tissue screen indicated high SCAI levels in the kidney." (PMID 29065889, 2017). "In cancer cells, it has been shown that MKL1 activity is strongly enhanced by down-regulation of its repressor SCAI (suppressor of cancer cell invasion)." (PMID 29065889, 2017). "Further study demonstrated that SCAI interacts with the tumor suppressing SWI/SNF (SWItch/Sucrose nonfermentable) chromatin remodeling complex to regulate gene expression and promote invasive capacities of human cancer cells." (PMID 26314959, 2015). "Although the molecular mechanism is currently unknown, regulation of SCAI (suppressor of cancer cell invasion), a nuclear negative regulator of MRTF may be relevant." (PMID 36717814, 2023).
tumor (13 papers, 2013 to 2025). "We show here that SCAI is functionally linked to SWI/SNF complexes to promote changes in gene expression that may be critical for tumor cell invasion." (PMID 23936361, 2013). "Thus the disruption of SCAI gene would abolish its repression on Rho protein mediated signal transduction and lead to the facilitating of cell migration, which contribute substantially to the metastasis of tumor." (PMID 27884161, 2016). "In particular, the well-studied tumor suppressor genes SCAI was found to be integrated by HPV16, which would likely disrupt its expression and therefore facilitate the migration of tumor." (PMID 27884161, 2016). "Our data show that SCAI interacts with the tumor suppressing SWI/SNF chromatin remodeling complex to promote changes in gene expression and the invasive capacities of human tumor cells." (PMID 23936361, 2013).
SCAI also shares sentences with these, for which no sentence is quoted: colorectal cancer (4 papers); Hypertension (2); cardiac hypertrophy (1); Cirrhosis (1); esophageal squamous cell carcinoma (1); hereditary hemorrhagic telangiectasia (1); hydatidosis (1); ischemic stroke (1); juvenile polyposis syndrome (1); migraine (1); non-small cell lung carcinoma (1); serous ovarian cancer (1).